RN7SL510P (RNA, 7SL, cytoplasmic 510, pseudogene)
Gene: Miscellaneous RNA gene on chromosome 15 (75,895,040 to 75,895,302, forward strand). Ensembl gene ENSG00000266308.
Homologues: Orthologues: chimpanzee Metazoa_SRP (86% identical), macaque Metazoa_SRP (85% identical). Paralogues in human: Metazoa_SRP (89% identical), RN7SL96P (89% identical), RN7SL488P (88% identical), RN7SL774P (88% identical), RN7SL163P (87% identical), Metazoa_SRP (87% identical), RN7SL596P (87% identical), Metazoa_SRP (86% identical), RN7SL134P (86% identical), RN7SL190P (86% identical), RN7SL391P (86% identical), RN7SL470P (86% identical), and 713 more.